LOX (lysyl oxidase)
Diseases named in the same sentence as LOX in open-access papers (continued):
Sharing a sentence is not in itself a finding about the gene and the disease.
preeclampsia (2 papers, 2019 to 2020). Preeclampsia is a hypertensive disorder of pregnancy that is characterized by new-onset hypertension with proteinuria presenting after 20 weeks of gestation, and depending on mild or severe forms may initially present with severe headache, visual disturbances, and hyperreflexia. "There is consistent data to support TGF- β1/Smad3 signaling-driven LOX induction resulting in cellular fibrotic mechanism, multiple tissue fibrosis, ventricular remodeling and impaired trophoblast invasion in preeclampsia." (PMID 32708046, 2020). "Trophoblast cell invasion can be inhibited by the decreased expression of LOX proteins; therefore, it was reasonable to believe that LOX protein expression is reduced in placental tissues from preeclampsia patients." (PMID 30804321, 2019). "The involvement of the TGF-β /SMAD3 pathway in regulating LOX expression was also confirmed in preeclampsia, a pregnancy-specific condition, in which decreased LOX was shown to be in close association with impaired trophoblast invasion in preeclamptic placenta." (PMID 32708046, 2020). "Thus, we compared the expression levels of LOX proteins in placental tissues from normal pregnant women and preeclampsia patients." (PMID 30804321, 2019). "Overall, these findings indicate that collagen accumulation caused by the downregulation of LOX and LOXL2 may be a key factor in suppressing trophoblast cell migration and invasion in preeclampsia." (PMID 30804321, 2019). "Considering the localization of LOX proteins in trophoblasts from first-trimester villi and the downregulation of LOX and LOXL2 in preeclamptic placentas, we speculated that loss of function of LOX or LOXL2 in trophoblast cells is critical for preeclampsia." (PMID 30804321, 2019). "Furthermore, evaluation of clinical samples revealed that downregulation of LOX and LOXL2 and upregulation of collagen were associated with preeclampsia." (PMID 30804321, 2019). "Considering the complex roles of LOX proteins in tumor cell invasion, we speculated that members of the LOX family are potentially involved in preeclampsia pathogenesis by interfering with the biological behavior of trophoblasts." (PMID 30804321, 2019). "Our results showed that both mRNA and protein expression of LOX and LOXL2 was decreased in placentas from patients with preeclampsia." (PMID 30804321, 2019). "Collectively, our study suggests that the downregulation of LOX and LOXL2 leading to reduced trophoblast cell migration and invasion through activation of the TGF-β1/Smad3/collagen pathway is relevant to preeclampsia." (PMID 30804321, 2019). "Here we revealed that lysyl oxidase (LOX) and LOX-like protein 2 (LOXL2) play a critical role in preeclampsia." (PMID 30804321, 2019). "Our study demonstrated that downregulation of LOX and LOXL2 is relevant to preeclampsia." (PMID 30804321, 2019). "Thus, we proposed that LOX, LOXL2, and the TGF-β1/Smad3/collagen pathway can serve as potential markers and targets for clinical diagnosis and therapy for preeclampsia." (PMID 30804321, 2019). "Thus, our findings suggest that LOX, LOXL2, and the TGF-β1/Smad3/collagen pathway are potential markers and targets for clinical diagnosis and therapy for preeclampsia." (PMID 30804321, 2019). "Thus, future research in uncovering direct LOX- and LOXL2-mediated molecules may provide deeper insights into the function of LOX and LOXL2 in preeclampsia." (PMID 30804321, 2019).
psoriasis (2 papers, 2023). An autoimmune condition characterized by red, well-delineated plaques with silvery scales that are usually on the extensor surfaces and scalp. "From the current perspective, this excess of 12(R)HETE comes from the high expression of 12(R)-LOX together with the availability of arachidonic acid found in psoriasis." (PMID 36837912, 2023).
pulmonary hypertension (2 papers, 2014 to 2022). Increased pressure within the pulmonary circulation due to lung or heart disorder. "In this study, we identified a novel mechanism in which chronic hypoxia caused increased Cu transport and LOX activity that promoted the development of pulmonary hypertension in a murine model." (PMID 24614111, 2014). "Our results are by another report that LOXL2 inhibition by lysyl oxidase inhibitor, β-aminopropionitrile, attenuated right ventricular hypertrophy, and normalized collagen crosslinking in hypoxia-exposed pulmonary hypertension mice." (PMID 36159334, 2022).
skin tumor (2 papers, 2020 to 2022). "The high levels of LOX, LOXL2, and LOXL4 transcripts in α11-deficient CAFs are congruent with the observed formation of extensive, linear collagen bundles and a shift toward stiffer skin tumor tissue in this mouse strain." (PMID 36003785, 2022). "Considering these data regarding PDAC, our observations regarding the defects in the activation of matrix-producing CAFs, LOX upregulation, and the formation of dense and aligned collagen matrix and the impaired growth of skin tumors in Itga11-/- mice are not necessarily contradictory." (PMID 36003785, 2022).
Stomach adenocarcinoma (2 papers, 2021 to 2024). "The connection between LOX expression and tumor immune infiltration in stomach adenocarcinoma (STAD) is, however, not yet understood." (PMID 35047494, 2021).
thyroid tumor (2 papers, 2020 to 2021). A benign or malignant neoplasm affecting the thyroid gland. "We found stromal CAF recruitment at the tumor invasive front associated with collagen deposition and LOX expression by the adjacent thyroid tumor cells." (PMID 31906302, 2020). "According to the model, CAFs are recruited in the stroma at the tumor invasive front where they synthesize and deposit collagen (COL1A1), which is in turn cross-linked by the enzyme LOX, produced by thyroid tumor cells." (PMID 31906302, 2020). "Expression of α-SMA-positive CAFs was found to be closely associated with stromal expression of COL1A1, whereas lysyl oxidase (LOX) was expressed by adjacent thyroid tumor cells." (PMID 33808627, 2021). "Overall, we showed the concurrent expression of α-SMA, LOX, and COL1A1 genes and proteins in BRAF-driven human thyroid tumors, where we also detected stroma associated local invasion." (PMID 31906302, 2020). "COL1A1 localized in tumor stroma and was closely correlated with α-SMA positive CAFs, whereas LOX was expressed by thyroid tumor cells." (PMID 31906302, 2020). "As validation of the proposed model, they investigated the expression of LOX and COL1A1 genes in human TC by using two public datasets and confirmed their upregulation in thyroid tumors as well as the association with BRAF mutation, but not RAS mutation." (PMID 31906302, 2020).
uveal melanoma (2 papers, 2014). A melanoma derived from melanocytes of the uveal tract. "To explore the role of HIF-1α in uveal melanoma, we first determined the baseline expression of HIF proteins and the mRNA levels of their downstream targets VEGF and LOX in uveal melanoma lines grown for 24 hours in normoxia (21% pO2) or hypoxia (1% pO2)." (PMID 25166211, 2014).
viral infection (2 papers, 2025). "Concurrently, genes associated with hypoxic stress, including PDK1, BNIP3L, VEGF, and LOX, were significantly upregulated in both EBOV- and MARV-infected HCOs, consistent with prior reports of hypoxia-related signaling during viral infection." (PMID 41284734, 2025). "While several collagen genes were downregulated at day 10, the elevated collagen accumulation could possibly be explained by enhanced crosslinking and stabilization of collagen via lysyl oxidase (Lox), which shows a sustained upregulation in H1N1-E158A virus infection." (PMID 40909698, 2025).
abscess (1 paper, 2014). An inflammatory process characterized by the accumulation of pus within a newly formed tissue cavity which is the result of a bacterial, fungal, or parasitic infection or the presence of a foreign body. "Additional hinokitiol in the calcium-hydroxide-based dental canal sealers might improve COX-2-associated inflammation, HIF-1α-associated inflammation, and LOX-associated S. aureus abscess formation potentials in vitro." (PMID 24915566, 2014). "LOX is associated with a critical and formerly unrecognized role in S. aureus abscess formation." (PMID 24915566, 2014).
acute megakaryoblastic leukemia (1 paper, 2023). Acute megakaryoblastic leukemia (AMKL) is a form of acute myeloid leukemia (AML) that occurs predominantly in childhood and particularly in children with Down syndrome (DS-AMKL). "Lysyl oxidase (LOX), which has roles in pediatric acute megakaryoblastic leukemia and in the creation of a growth permissive fibrotic microenvironment, was associated with increased extramedullary disease in adults with AML and high plasma LOX activity." (PMID 36900239, 2023).
adenoma (1 paper, 2021). A neoplasm arising from the epithelium. "The total number of aldehydes incorporated into cross-linking (DHLNL + HLNL + 2 × Pyr + 2 × d-Pyr + 2 × HHMD) was also significantly increased in neoplastic mammary tissue samples (p < 0.05), indicating that LOX is highly active in carcinoma and adenoma, producing increased amounts of cross-links." (PMID 33883562, 2021).
adhesive capsulitis (1 paper, 2016). "In the present study, we quantified the mRNA expression of the TGFβ1, TGFβR1, LOX, PLOD1, PLOD2, COMP, FN1, TNC and TNXB genes in glenohumeral synovium/capsule samples collected from patients with adhesive capsulitis and from controls." (PMID 27438566, 2016).
adolescent idiopathic scoliosis (1 paper, 2011). A scoliosis with no known cause arising in adolescent. "We hypothesized that common polymorphisms in the five human lysyl oxidase genes (LOX, LOXL1, LOXL2, LOXL3, and LOXL4) may be associated with the phenotype of adolescent idiopathic scoliosis." (PMID 21740577, 2011).
allergic conjunctivitis (1 paper, 2022). "Interestingly, the LOX level was also elevated in corneas with allergic conjunctivitis but reduced by prednisone acetate treatment." (PMID 35692541, 2022).
Alport syndrome (1 paper, 2020). A rare renal disease characterized by glomerular nephropathy with hematuria progressing to end-stage renal disease (ESRD), frequently associated with sensorineural deafness, and occasionally with ocular anomalies. "From this study, Dr. Nabity has discovered new genes that are differentially expressed between the slow and rapid progressing animals with Alport syndrome, including lysyl oxidase (LOX) transcripts." (PMID 31044288, 2020).
amyotrophic lateral sclerosis (1 paper, 2005). Amyotrophic lateral sclerosis (ALS) is a neurodegenerative disease characterized by progressive muscular paralysis reflecting degeneration of motor neurons in the primary motor cortex, corticospinal tracts, brainstem and spinal cord. "The lysyl oxidase (LOX) has been found at elevated levels in amyotrophic lateral sclerosis (ALS) and in superoxide dismutase (mSOD1) knockout mice (which exhibit an ALS-like syndrome) and is believed to be involved in the progression of ALS." (PMID 16029492, 2005).
aneurysmal diseases (1 paper, 2019). "Therefore, aneurysmal diseases are associated with suppression of vascular LOX activity, while experimental interventions or pathophysiological compensatory responses increasing LOX activity seem to preserve artery integrity." (PMID 31615160, 2019).
Ascending aortic dissection (1 paper, 2022). A separation of the layers within the wall of the ascending aorta. "There are many similar rare mutations in common pathogenic genes, with the identification of heterozygous rare variants c.839G > T (p.Ser280Arg) and c.893T > G (p.Met298Arg) missense mutations in LOX, encoding a lysyl oxidase, leading to the development of ascending aortic dissection." (PMID 36588568, 2022).
autism spectrum disorder (1 paper, 2025). A spectrum of developmental disorders that includes autism, and Asperger syndrome. "In this study, through the analysis of CHD8A and CHD8B allelic deletion samples, we identified seven hub genes associated with Autism Spectrum Disorder (ASD): IGF2, FN1, CXCR4, COL11A1, ITGA6, LOX, and FBN2." (PMID 40526590, 2025).
basal cell carcinoma (1 paper, 2013). A carcinoma involving the basal cells. "The lack of LOX protein in tumor cells originating from keratinocytes is clearly associated with human basal cell carcinoma and squamous cell carcinoma skin cancers." (PMID 23425977, 2013).
benign breast diseases (1 paper, 2022). "A recent study reported that serum Cu level in BC patients was significantly higher than in healthy controls and patients with benign breast diseases, and copper can be transported to lysyl oxidase (LOX) family members, thus contributing to cancer metastatic." (PMID 36518756, 2022).
benign prostate hyperplasia (1 paper, 2018). "LOX expression is lower in PCa tissues than in benign prostate hyperplasia (BPH) nodules, and is also reduced in metastases compared with primary PCa tissues, suggesting LOX decline during progression to metastasis." (PMID 29732010, 2018).
bone metastasis (1 paper, 2021). Transfer of a neoplasm from its primary site to bones. "LOX has previously been demonstrated to remodel the pre-metastatic niche in the bone by enhancing osteoclastogenesis and inducing osteolysis in a spontaneous bone metastasis mouse model." (PMID 33919988, 2021).
bone tumors (1 paper, 2016). "Consideration of this possibility together with the evaluation of Endo180 and LOX as targets in pre-clinical models of osteolytic bone tumors induced by PC3 and DU145 cells and predominantly osteosclerotic tumors induced by VCaP cells will be prioritised in our future work." (PMID 26567111, 2016).
brain ischemia (1 paper, 2023). Diminished or absent blood supply to the brain caused by obstruction (thrombosis or embolism) of an artery resulting in neurologic damage. "Though not challenged in the present study, other bioactive products of 20:4n6 and other polyunsaturated fatty acids oxidation, including LOX-dependent metabolites and non-enzymatic products of oxidation which have an important role under brain ischemia, might be regulated by the same mechanism." (PMID 37783389, 2023).
Bruck syndrome (1 paper, 2023). Bruck syndrome is characterized by the association of osteogenesis imperfecta and congenital joint contractures. "Mutations of the LOX gene have been identified in Bruck syndrome, a rare, genetic disease with a phenotype similar to OI." (PMID 37373151, 2023).
cerebral small vessel disease (1 paper, 2021). Cerebral small vessel disease is the term currently used to pathological processes that affect the brain parenchymal circulation (arterioles, capillaries, and veins). "Disruption of the vascular ECM has been hypothesised to be a key component in pathogenesis of cerebral small vessel disease, particularly in monogenic forms, and several of the genes implicated in this study (COL4A2, LOX, SH3PXD2A, GPR126, HTRA1) have key roles in the ECM." (PMID 33773637, 2021).
chronic lung disease (1 paper, 2014). According to the definitions of the American and British Thoracic Societies, including pulmonary functional tests, X-rays, and CT scans for items such as fibrosis, bronchiectasis, bullae, emphysema, nodular or lymphomatous abnormalities. "Both elastin and the lysyl oxidase content are increased in infants with chronic lung disease of prematurity." (PMID 24661418, 2014).
collagenopathies (1 paper, 2021). "LOXL3, known for its function as a lysyl oxidase, has been associated with embryonic development and diverse pathologies, including collagenopathies and fibrosis." (PMID 34360836, 2021).
copper metabolism disorders (1 paper, 2022). "LOX inactivation due to copper metabolism disorders or genetic mutations leads to the dysfunction of connective tissue." (PMID 36072790, 2022).
cystadenoma (1 paper, 2015). A benign or borderline cystic epithelial neoplasm arising from the glandular epithelium. "Regrouping of the seven histotypes into three groups: cystadenoma, borderline cystadenoma and carcinoma, according to their outcomes, revealed that patients with carcinoma expressed significantly more CD41, BCAR1, LOX, FAK, VEGF and MVD compared with the borderline or cystadenoma groups." (PMID 25502723, 2015).
dementia (1 paper, 2025). Loss of intellectual abilities interfering with an individual's social and occupational functions. "LOX activity was reported to be increased in post mortem brains of patients with AD and dementia compared to control subjects." (PMID 40465757, 2025).
diabetic cardiomyopathy (1 paper, 2023). Diabetic cardiomyopathy is a disorder of the heart muscle in people with diabetes. "In silico predictive methods support that LOX-like 2, a LOX isoform known to play an important role in ECM cross-linking, can be used as an early biomarker for diabetic cardiomyopathy." (PMID 37764732, 2023).
diabetic foot ulceration (1 paper, 2016). "The aberrant collagen microenvironment due to elevated MMPs, LOX, and alteration of dermal mechanical properties could serve as a risk factor for diabetic foot ulceration." (PMID 27104752, 2016). "Our finding that chronic and progressive alterations of the dermal collagenous microenvironment due to constitutive elevation of MMPs and LOX may have a profound effect on non-healing in diabetic foot ulceration." (PMID 27104752, 2016).
diffuse gastric adenocarcinoma (1 paper, 2021). An adenocarcinoma arising from the stomach. "Chen gastric statistics indicated that LOX is overexpressed in gastric intestinal adenocarcinoma compared with gastric normal tissue with a fold change of 2.312, diffuse gastric adenocarcinoma with a fold change of 2.004, and gastric mixed adenocarcinoma with a fold change of 3.232." (PMID 35126449, 2021).
dysplasia (1 paper, 2019). A usually neoplastic transformation of the cell, associated with altered architectural tissue patterns. "In dysplasia, LOXL2 and LOX were highly expressed in the outer keratinized oral epithelium, with some staining observed extending into the stratum spinosum." (PMID 31086173, 2019).
enteropathies (1 paper, 2017). "Administration of a novel COX/LOX inhibitor, an H2S releasing compound 2C3DHTA demonstrated a significant cytoprotective effect in all used models of drug-induced enteropathies." (PMID 29064425, 2017).
enthesitis (1 paper, 2021). Inflammation at the site of insertion of ligaments, tendons, and other fibrous structures into bone. "Since oxylipins associated with enthesitis belong to COX2 and LOX pathways, dual inhibition could be beneficial in patients with enthesitis." (PMID 34303373, 2021).
epidermolysis bullosa (1 paper, 2021). Epidermolysis bullosa (EB) is a group of genetic skin diseases that cause the skin to blister very easily. "While this has not been documented for MMP yet, studies of injured human skin of recessive dystrophic epidermolysis bullosa patients showed higher levels of lysyl oxidase." (PMID 35197965, 2021).
epilepsy (1 paper, 2018). A brain disorder characterized by episodes of abnormally increased neuronal discharge resulting in transient episodes of sensory or motor neurological dysfunction, or psychic dysfunction. "The LOX pathway-derived metabolites of AA, 5(S)-HETE, 8(S)-HETE, 12(S)-HETE, 15(S)-HETE, 19(S)-HETE and 20-HETE, remained unaltered with epilepsy and upon PEA treatment (data not shown), indicating a specific role of COX-2 mediated inflammation induced by epilepsy." (PMID 29593494, 2018).
erectile dysfunction (1 paper, 2018). Persistent or recurrent inability to achieve or to maintain an erection during sexual activity. "We explored the role of lysyl oxidase (LOX) in rat and human penes after ischemic priapism (IP) to verify the effects of anti‐LOX in relieving penile fibrosis and preventing erectile dysfunction caused by IP in rats." (PMID 29278308, 2018).
estrogen-receptor negative breast cancer (1 paper, 2017). "It was recently demonstrated that LOX secretion was specifically associated with metastasis to the bone in patients with estrogen-receptor negative breast cancer." (PMID 28425924, 2017).